RNU7-88P (RNA, U7 small nuclear 88 pseudogene)
Gene: Small nuclear RNA gene on chromosome 13 (59,480,070 to 59,480,132, forward strand). Ensembl gene ENSG00000239003.
Homologues: Orthologues: chimpanzee U7 (100% identical), macaque U7 (98% identical). Paralogues in human: RNU7-48P (86% identical), RNU7-50P (86% identical), RNU7-70P (86% identical), RNU7-55P (84% identical), RNU7-57P (84% identical), U7 (84% identical), RNU7-103P (83% identical), RNU7-104P (83% identical), RNU7-136P (83% identical), RNU7-148P (83% identical), RNU7-172P (83% identical), RNU7-2P (83% identical), and 143 more.